CD4 (CD4 molecule)
Diseases named in the same sentence as CD4 in open-access papers (continued):
Sharing a sentence is not in itself a finding about the gene and the disease.
infection (continued). "Patients receiving STR were indeed younger, more often male, had higher CD4 and lower HIV RNA level and had less often a CDC stage C suggesting that these patients had somehow less severe infection than patients receiving a non-STR regimen." (PMID 28152047, 2017). "Similar to that seen in our primary infection experiments, the CD3+ T cell population observed in weanlings from infected mothers consisted primarily of CD3+CD4- and CD3+CD8- T cells that were not present in controls from non-infected mothers." (PMID 28178290, 2017). "In the absence of adequate CD4 T cell help, CD8 T cell population is unable to maintain optimal polyfunctionality, which is needed for controlling the infection." (PMID 29163509, 2017). "We introduced MPA after exposure of the CD4+ T cells to HIV, to ensure that differential activation of CD4+ T cells was not a confounding factor, whereas Sampah and Huijbregts treated CD4+ T cells with MPA prior to infection with HIV." (PMID 29255206, 2017). "On day 4 post infection with MCMV-HEL, no IL-17 production was found in HEL-specific CD4+ T cells in either nTg control mice or sTg-IRBP:HELhi mice, but these CD4+ T cells produced IFN-γ." (PMID 29079770, 2017). "The key factors contributing to the benign nature of these infections are the absence of chronic immune activation and a different pattern of SIV cellular targeting in vivo, which preferentially preserves CD4+ TCM and stem-cell memory cells or TSCM." (PMID 27227993, 2016). "Conversely, infection of human and NHP MDM stimulated a moderate cytokine response, but infected human MDM did not stimulate CD4+ T cells." (PMID 27191161, 2016). "We previously showed profound alterations of CD4+CD8+ double positive and CD4−CD8−double negative populations during infection." (PMID 26745276, 2016). "When we analyzed the single-cell suspensions from dissociated lungs after Ad Foxp3-EGFP or Ad-EGFP infection, Foxp3 was expressed in CD326+ epithelial cells, but not in CD4+ or CD8+ cells." (PMID 27633092, 2016). "Consistently, the surviving CD4+YFP+GFP+ T cell–derived cells were unresponsive and failed to proliferate during the early phase of secondary infection." (PMID 27630165, 2016). "At late time points after infection (day 7), LASV-infected mice showed a significant increase in the frequency of CD8 T but not CD4 T cells compared to MORV-infected mice in both spleen and lungs." (PMID 27191716, 2016). "HIV infection can occur cell-free via infection by HIV particles or by cell–cell contact between HIV-1 infected T cells or dendritic cells and non-infected CD4+ target T cells at a virological synapse." (PMID 27783038, 2016). "Although a 2-fold increase in the frequency of CD11c+ cDC and a 3-fold increase in CD4+MHC class II+ pDC was observed, these changes were not statistically different to the levels detected prior to infection." (PMID 27008425, 2016). "We show that, although all HAMB increased HIV infection and depletion of LP CD4 T cells to some degree, gram-negative HAMB appeared to enhance infection and depletion to a greater extent than gram-positive HAMB." (PMID 26762145, 2016). "Memory CD4 and CD8 T cells can provide strong protection in the absence of neutralizing Ab following heterosubtypic infection in mouse models of IAV infection." (PMID 27148257, 2016). "Our data reveal that signaling through Dectin-1 differentially controls the ability of DCs to induce CD4+, but not CD8+, T-cell responses during infection in vivo." (PMID 26349660, 2016). "More globally, subjects with neuroinvasive infections had reduced numbers of CD4+FoxP3+ Tregs that were CTLA4 positive and exhibited a distinct upregulated transcript profile that was absent in subjects with asymptomatic infections." (PMID 26795118, 2016). "Following L. monocytogenes-infection, listeria-specific IRF4−/− CD4+ T cells showed impaired TH1 differentiation and failed to expand to the level observed for WT CD4+ T cells." (PMID 27762344, 2016).
infection (continued). "One hour after infection, viable bacteria were isolated from the CD4+ or CD8+ cells for all three species, which did not survive 24 hours after infection." (PMID 27383402, 2016). "In light of that, the negative correlation between time to ART initiation after infection and the levels of IFN-γ+ HIV-specific CD4 responses maintained at month 6 further supports the importance of early treatment." (PMID 27746782, 2016). "Notably, the antiserum only had significant protective role against similar bacteria, while adoptive transfer of lymphocytes significantly controlled the spread of the virulent heterologous serogroup PAO-6 infection, and the protective role could be reversed by CD4 rather than CD8 antibody." (PMID 26879055, 2016). "One potential candidate, carbohydrate binding agents (CBAs) has been shown to prevent CD4 T cell HIV infection, cell–cell fusion, binding to DC-SIGN and trans-infection of CD4 T cells without affecting the growth of commensal Lactobacilli." (PMID 26968525, 2016). "However, CCL19-treated resting CD4+ T cells had a pattern of integration that differed significantly from the other in vitro conditions, suggesting HIV integration site selection may depend on the balance of transcription factors, including NF-κB, at the time of infection." (PMID 27459960, 2016). "An unexpected finding was that the immediate potency of HSV-2 immune responses within single infection microenvironments appears similar in HIV positive and negative men regardless of CD4+ T-cell count." (PMID 27285483, 2016). "There was a slight increase in the frequency of CD4+ T cells and CD8+ T cells in the stat3f/f;CD19Cre/+ mice compared to control stat3f/f mice, regardless of the route of infection." (PMID 27486189, 2016). "Myeloid expansion and control of infection require production of the signaling protein Macrophage Colony Stimulating Factor (MCSF) by multiple sources, including CD4+ T cells, which had not previously been known to make this protein in a physiological setting." (PMID 27923070, 2016). "Early in the course of primary infection (day 7), comparable levels of CD8+ T cells, dendritic cells, B cells, NK cells, macrophages, and neutrophils were present in CD4-depleted and nondepleted mice." (PMID 27600502, 2016). "While not all donors required CCL19 to facilitate direct infection of resting CD4+ T-cells, adding CCL19 ensured consistent infection of resting CD4+ T-cells in vitro." (PMID 27383184, 2016). "Hepatic NKT cells consisted mainly of CD1d-dependent CD4+ and double negative NKT cells, whereas splenic NKT cells presented a CD1d-independent TCRhigh CD4high phenotype during infection." (PMID 27446022, 2016). "Thus, the downregulation of NKp44-activating ligands on infected CD4 T cells might serve as an immune escape mechanism, while NKp44 ligand expression on non-infected CD4 T cells may contribute to the overall depletion of CD4 T cells over the course of infection." (PMID 27446081, 2016). "The results from the β2m0 or Aβ0 mice indicate that neither independent CD4+ nor CD8+ T cells are required for early limitation of virus replication in the brain, since these mice survive the acute infection." (PMID 27855706, 2016). "CD107a expression was similar in CD4 and CD8 T cells, unlike perforin and granzyme B. CD107a slightly increased in expression in CD4 and CD8 T cells over the course of infection." (PMID 27760221, 2016). "CD4 T cells infected with HIV-1 LAI were cultured with or without 100nM panobinostat for 24 hours, at 48 hours post infection." (PMID 27529554, 2016). "Instead, we observed that the majority of CD4+ T cells in the peripheral blood are refractory to HIV infection regardless of titer and that single and double infection are restricted to a small population of cells." (PMID 26559763, 2015). "Non-cycling memory CD4+ T lymphocytes are, in fact, the principal targets of both HIV and SIV during the initial weeks of the acute in vivo infection." (PMID 25996507, 2015).
infection (continued). "Surprisingly however, during LCMV cl 13 infection, the effect of GITR was largely CD4 T cell-intrinsic and independent of Tregs." (PMID 25590581, 2015). "FACS analysis of blood samples showed that treatment with ABX464 prevented depletion of CD4+ cells following infection of reconstituted mice and thereby restored the CD8+/CD4+ ratio back to that of non-infected mice." (PMID 25889234, 2015). "In resting CD4+ T cells, as observed with the other HIV-2 strains, the GL-AN viruses did not lead to productive infection." (PMID 25582927, 2015). "Since these CD4+ cells are not supposed to react to OVA, their expansion was most likely due to the presence of FusOn-H2 infection." (PMID 25460506, 2015). "The median CD4+ cell counts of PLWHAs and HIV negative individuals were not statistically different, and median post-infection increases in anti-peptide IgG were similar in both groups of patients." (PMID 25906165, 2015). "Unlike primate lentiviruses, SRLVs do not use CD4, CCR5, and CXCR4 molecules as receptors/coreceptors for target cell infection." (PMID 29061947, 2015). "Cell depletion and transfer experiments indicated that during infection the absence of NK, NKT and CD8+ T cells, but not CD4+ T cells, resulted in a reduced anemic phenotype similar to trypanosome infected IFNγR-/- mice." (PMID 26070118, 2015). "Extended subtyping of 410 non-B infections was performed and patient demographics, HIV transmission route, co-receptor use, viral load and CD4 count were compared between subtypes." (PMID 26572861, 2015). "The model did not consider the process of hemodilution, in which CD4 counts in HIV-infected pregnant women are lower than in HIV-infected, non-pregnant women, after adjusting for time of infection." (PMID 26262889, 2015). "In contrast, gating on either CD4+ or CD8+ T cells on days 6 and 10 post-infection revealed no changes in the extent of EdU incorporation between the two groups of animals." (PMID 26709698, 2015). "It is important to point out that our results in no way exclude the protective role of CD4+ T cells and IFN-γ during infection with the parasites." (PMID 26222157, 2015). "The viruses with the wt and S375W Envs infected the CfTh-CD4/CCR5 cells, but the viruses with the I559P Envs did not support infection (data not shown)." (PMID 25849367, 2015). "In activated CD4+ T cells, HIV latency is established within the first few days of infection and does not require the cell to return to a resting state." (PMID 26067822, 2015). "There were fewer TCRβ+CD4+ T cells in the lungs of BMT mice compared to BALB/c mice both before and after infection, although these differences were not statistically significant." (PMID 26407316, 2015). "The control of infection in animals lacking both CD8+ and CD4+ T cells as well as B cells was surprising given the fact that RAG-/- animals, which do not contain functional T and B cells, are not capable of controlling MCMV." (PMID 25658831, 2015). "On the other hand, infection with DRV-NG11 fails to induce the activation of DCs and B cells and further reduces CD4 T cell production." (PMID 26292099, 2015). "At 180 days post bi, splenic ex vivo CD4+ and CD8+ TEM cells increased by 20–44% only in response to challenge infection (with or without in vitro antigenic stimulation) with no change in the TCM population." (PMID 25951312, 2015). "By an analysis of variance (ANOVA) method, CD4 T-cells differed significantly between the ART regimen arms (p = 0.006) and infection statuses (p<0.001) but not between age groups or gender." (PMID 26208212, 2015). "Due to the defects in regulatory T cell populations in Irf4fl/fl mice, CD4+ and CD8+ T cell populations are activated in Irf4fl/fl mice even in the absence of infection." (PMID 26714260, 2015). "The lack of infection found in the uterus of this animal either by IVIS, or nested PCR is consistent with the lack of CD4+ T cells and macrophages in the uterine endometrium late in the menstrual cycle." (PMID 25299616, 2014).
infection (continued). "Praziquantel efficacy, as measured by parasitological cure rates and reduction in the intensity of the infection, did not vary significantly with the HIV-1 serostatus and was not influenced by the level of CD4+ cell counts." (PMID 25671125, 2014). "During the PE period, the slightly but not significantly higher levels of CD4+CD8α– T helper cells and γ/δ T lymphocytes in the PCV2-vac group were attributed to changes independent of infection." (PMID 24735253, 2014). "Infection through CCR5 frequently generated viral-induced MGC, while coreceptor-negative NP-2/CD4 cells did not form any cluster of nuclei (data not shown)." (PMID 24980635, 2014). "At the CP, the silent and severe infection groups had no significant changes in the counts of CD3+, CD4+, and CD8+ cells relative to baseline; however, these counts were greater than the control group at baseline (p ≤ 0.001 for all comparisons)." (PMID 24646014, 2014). "This is supported by our data, as tethering CD4 to the cell surface, using LCK, increased HIV-1 fusion but did not increase productive infection." (PMID 24465876, 2014). "During MHV68 infection of C57BL/6 mice, perforin is critical in maintaining latency in the spleen and controlling viral recrudescence in the lung in the absence of CD4 T cells." (PMID 24587276, 2014). "While we investigated the CD8+ response and the chemokine MIP-1β, a chemokine important for recruitment of additional immune cells to sites on infection and produced by activated CD8+ and CD4+ cells, no clear patterns of CD8+ or MIP-1β responses were observed." (PMID 25397604, 2014). "Unfortunately, in agree with previous reports, we did not found any significant difference in CD4+ cell counts and HIV load with regard to the GBV-C infection status among patients with HIV/HCV coinfection." (PMID 24693316, 2014). "Unlike CD4+ response, the cytokine response of CD8+ T cells before infection did not demonstrate clear reflection of the protection data." (PMID 25500571, 2014). "During natural infection, the HIV envelope proteins gp120/gp41 interact with the cell surface receptors CD4 and CCR5 and mediate entry through fusion rather than endocytosis as is the case for VSV-G pseudotyped virions 89,90." (PMID 24782340, 2014). "Numbers of CD4+ and CD8+ T cells are substantially reduced in fatal human and nonhuman primate (NHP) infections before death." (PMID 25699183, 2014). "Some HIV patients are able to maintain stable CD4 cell counts for an extended time and remain asymptomatic without ART for years after infection." (PMID 25495598, 2014). "In BAL CD3+ T cells were increased following infection and this appeared to consist predominantly of CD8+ T cells, as CD4+ T cells in BAL were not significantly increased." (PMID 24099891, 2014). "No remarkable difference was noted in the percentages of CD4+ T cells, B cells (CD19+) and dendritic cells between the two groups with H7N9 infection." (PMID 24664315, 2014). "Despite low rates of infection by HIV-1, DCs can efficiently capture HIV-1 and mediate potent viral transmission, thus promoting a vigorous infection of CD4+ T cells in the absence of productive DC infection or innate immune detection." (PMID 25033082, 2014). "The reduction in weight loss was matched by a significant reduction in the number of NK cells and their activation at both day 4 and day 7 after infection and CD8 T cells at day 7 after infection, but no change in CD4 T cell recruitment." (PMID 24173217, 2014). "So to examine possible involvement of IP-10 in the secretion of TGF-β from CD4+CD25+ Treg cells following SLA–CpG–DCs vaccination, we vaccinated the mice, infected it with Leishmania and monitored the course of infection in the presence or absence of IP-10." (PMID 24926293, 2014).
infection (continued). "A previous paper from the same group demonstrated that quiescent CD4 T cell death required other cells or cell factors in HLAC and that isolated peripheral CD4+ T cells did not undergo cell death upon abortive infection with HIV." (PMID 24788318, 2014). "CD4 T-cell decline was rapid, there were no anti-HIV antibody responses, and viral production was mainly from macrophages at the later stages of infection." (PMID 25256394, 2014). "CD4+ IL-17A+ RORγt+ Th17 cells are activated during acute P. berghei ANKA and P. yoelii infection, but the function of these cells during infection was not explored." (PMID 25628621, 2014). "The TcVac3-dependent expansion of CD4+ and CD8+ T cell response to challenge infection was not significantly altered when cytokine adjuvants were co-delivered with the 1st-dose of vaccine." (PMID 23555672, 2013). "Accordingly, increased numbers of CD4+CD25+ cells were found in the C57BL/6 infected mice at day 7, but not at day 4 upon infection." (PMID 23937079, 2013). "Nondividing CD4+ T-lymphocytes and myeloid cells including monocytes, DCs, and macrophages play an important role in establishment of HIV-1 initial infection and viral transmission." (PMID 24523981, 2013). "Thus, as CD4+ T cells recognize antigen sampled from either the intracellular or extracellular milieu, a specific CD4+ T cell response may be secondary to prior antigen-sensitization by Mtb rather than ongoing, intracellular infection." (PMID 24324704, 2013). "Using a pathology score that goes from 0 to 5, where 0 is mild and 5 is severe disease, at 7 weeks post-infection RAG+CD8 mice had the most severe disease followed by Rag1−/− mice with moderate disease and RAG+CD4+CD8 mice with no disease." (PMID 23874205, 2013). "Although PD-1 has been well characterized as a negative regulator of conventional CD4+ T cells, the role of PD-1 and its interaction with PD1 ligands in regulating activation and function of iNKT cells after infection with IAV has not been investigated." (PMID 23555047, 2013). "Since our results suggest that E2 is affecting viral entry, without down-regulating CD4 and CCR5 expression, we explored the possibility that E2 treatment alters ligand secretion of RANTES and MIP-1β, known to block HIV-infection through CCR5 binding." (PMID 23614015, 2013). "In CD4 T cells though, the difference in CCR5 expression between PD-1+ and PD-1 negative cells gradually decreased from pre infection to 4 months post infection, suggesting elimination of these cells or increased extravasation of this subset into tissues." (PMID 23555918, 2013). "A strong inflammatory response was characterized by a high up-regulation of CD43 and a down-regulation of CD62L in both CD4+ and CD8+ T cells at 8 days post-infection (not shown)." (PMID 24367519, 2013). "These immature DC did not support cis infection with HIV-1 X4 virus but resulted in explosive virus replication when mixed with polyclonally activated, autologous CD4+ T cells." (PMID 24278768, 2013). "In agreement with our previous report and others, PD-1 expression on total CD4 and CD8 T cells was not markedly altered during chronic SIV infection, compared with expression levels measured before infection." (PMID 23555918, 2013). "Our data also showed that there was no significant augmentation of PD-1 expression on CD4+ and CD8+ T cells during any time point post infection, consistent with our previous report." (PMID 23555918, 2013). "To test the effect of infection on T cells with specificity for non-schistosome antigens, we infected TCR-transgenic OT-II/RAG-1−/− mice that only possess OVA-specific CD4+ T cells." (PMID 23556020, 2013). "As expression of CD134 is restricted to activated CD4+ (not CD8+) T cells, FIV infection of the domestic cat results in an immune dysfunction characterised by a progressive depletion of helper T cells." (PMID 23372784, 2013).